PDGFA (platelet derived growth factor subunit A)
Diseases named in the same sentence as PDGFA in open-access papers (continued):
Sharing a sentence is not in itself a finding about the gene and the disease.
cancer (continued). "Further insight into the cancer-related gene expression unraveled that 22 of DEGs were upregulated by shNrf1, of which 4 genes (i.e., RAC3, PDGFA, GSTA4, and RXRA) were downregulated by Nrf1α−/− (, and )." (PMID 32273945, 2020). "High levels of PDGFA and PDGFB in CRC tissues were shown to correlate with poor cancer prognosis as well." (PMID 32316138, 2020). "Previous studies have shown that PDGFA, which binds and activates PDGF receptor tyrosine kinases, promotes cancer cell proliferation, invasion, and self-renewal." (PMID 31300060, 2019). "Among these genes, notably, platelet-derived growth factor A (PDGFA) and signal transducer and activator of transcription 3 (STAT3) were relevant according to the cancer pathway analyzed using NetworkAnalyst." (PMID 30068339, 2018). "Meanwhile, the functional enrichment analysis showed that PDGFA was involved in MAPK signaling pathway, pathways in cancer, and transcriptional dysregulation in cancer." (PMID 29212247, 2017). "With the aim of evaluating the effects of cancer cells upon the hASCs' capability of promoting angiogenesis, CD31, VEGF, PDGFA, PDGFRα, PDGFRβ gene expression was analysed at 7, 14 and 21 days." (PMID 28102844, 2017). "These genes belong to relevant intracellular signaling pathways in cancer such as PI3K-Akt (COL4A2, MYC, PDGFA, SPP1), proteoglycans (HIF1A, MYC, PLAUR, TGFB1), and Hippo (CTGF, MYC, NF2, TGFB1)." (PMID 29075357, 2017). "Targeting PDGFA/PDGFRA signaling could represent a therapeutic opportunity to treat fibrosis-related disorders and cancer." (PMID 40892943, 2025). "D’Agostino and Pearson omnibus normality test indicated that the expression of WNT10A, TNF, and PDGFA in various cancers did not normally distribute." (PMID 32434423, 2020). "For example, PDGFA and PDGFRA of the PDGF signaling pathway are targeted by approved drugs for other cancers and potentially could be exploited for use in ESCC." (PMID 22280838, 2012). "Our findings also suggest that similar PDGFA/PDGFRA signaling mechanisms may be employed in other contexts, such as recruiting fibroblasts during wound healing or regulating cell migration in pathological conditions like cancer metastasis." (PMID 40892943, 2025). "In addition, gene expression comparison among various types of cancers in TCGA PanCan databases showed that GBM held the highest mRNA level of PDGFA, but not the other three PDGF ligands, implying that PDGFA was particularly important for GBM." (PMID 35105853, 2022). "Hence, we speculate that PDGFA is probably also induced by either bFGF or insulin to lead to the autocrine mechanism of PDGF–PDGFR activation because PDGFR plays a crucial role in triggering and maintaining cancer stemness." (PMID 30068339, 2018).
bacterial infection (1 paper, 2023). "In summary, the present study is the first to demonstrate that treatment with the S1PR2 antagonist (JTE013) enhanced TGFβ/Smad and Akt signaling and increased VEGFA, PDGFA, and GDF15 gene expressions in murine BMSCs with or without bacterial infection." (PMID 36834810, 2023).
PDGFA also shares sentences with these, for which no sentence is quoted: cardiac hypertrophy (3 papers); emphysema (3); fibrosis (3); infection (3); liver cancer (3); neuroblastoma (3); adenoma (2); aneurysm (2); aortic aneurysm (2); arteriosclerosis (2); biliary atresia (2); chondrosarcoma (2); diabetic retinopathy (2); glomerulosclerosis (2); head and neck squamous cell carcinoma (2); Hyperinsulinemia (2); hypothyroidism (2); invasive ductal breast carcinoma (2); lung carcinoma (2); oligodendroglioma (2); osteosarcoma (2); papillary thyroid cancer (2); acute pancreatitis (1); anaplastic astrocytoma (1); arteriosclerosis obliterans (1); atrial septal defect (1); autoimmune disease (1); brain cancer (1); cardiac failure (1); cervical cancer (1).
A further 58 diseases each share a sentence with PDGFA in 1 paper.